TOP1 (DNA topoisomerase I)
Diseases named in the same sentence as TOP1 in open-access papers (continued):
Sharing a sentence is not in itself a finding about the gene and the disease.
cancer (continued). "TOP1 expression and cancer aggressivity in clinical cohorts." (PMID 35349486, 2022). "Consequently, this type of compound is of particular interest as anti-cancer drugs and indeed all known TOP1 targeting anti-cancer drugs including the water-soluble CPT derivatives, topotecan (TPT) and Irinotecan, belong to this family of drugs." (PMID 34452216, 2021). "In addition to endogenous and environmental DNA lesions, TOP1 is the target of anticancer drugs that kill cancer cells by trapping TOP1ccs4." (PMID 34408146, 2021). "Additionally, we measured TOP1 activity in biopsies from cancer patients and proved it possible specifically to detect the presence of human pathogens in crude clinical samples." (PMID 34452216, 2021). "The overexpression of BAZ1B, and therefore that of SMARCA5, could potentiate the function of TOP1 during DNA replication, affecting the response of cancer cells to TOP1 inhibitors and to other treatments affecting replication." (PMID 33802597, 2021). "Variable copy numbers of Top1 gene were reported in five different cultured human cancer cells." (PMID 35582377, 2021). "Mechanisms of irinotecan refractoriness could be overexpression of drug efflux transporters, elevated drug metabolism for detoxification, and changes in Top1, cancer cell phenotypes, and tumor microenvironment." (PMID 35582377, 2021). "In addition, a high TOP1 expression has also been demonstrated in several other cancers, including small cell lung, gastric/gastroesophageal, esophageal, thymic, anal, breast, prostate and poorly differentiated neuroendocrine carcinomas." (PMID 32530388, 2021). "However, in those CPT-resistant cancers with Top1 mutants that are catalytically defective but competent for DNA binding, additional consideration must be made according to some interesting preliminary data from yeast studies." (PMID 32059547, 2020). "The reduced levels of Top1 in the CPT-resistant human cancer cells is then expected to disrupt its normal cellular role of preventing the excess level of negative supercoiling at highly transcribed loci and to thereby elevate the accumulation of non-B DNA formation including G4 DNA." (PMID 32059547, 2020). "The increased potential for the G4-induced genome instability due to the catalytic Top1 mutant could render cancers more complicated to treat and potentially worsen patient outcomes." (PMID 32059547, 2020). "CuC inhibitors targeting Top1 or Top2 as DNA-damaging drugs or poisons arrest cancer cells in G2/M." (PMID 33027952, 2020). "CPT and CPT derivatives are widely used to treat many cancers, and work by stabilizing Top1-ccs." (PMID 32059547, 2020). "Additionally, CGs were known to act as inhibitors of IL8 production, DNA topoisomerase I and II, anoikis prevention and suppression of several target genes responsible for the inhibition of cancer cell proliferation." (PMID 32784680, 2020). "We next determined whether the observed chemosensitivity to SN38 across the four cancer cell models could be due to differences in expression levels of the SN38 target TOP1." (PMID 31067275, 2019). "Top1 poisons continue to be among the world’s most important anti-cancer drugs." (PMID 31930190, 2019). "Interestingly, some of the cancer cell lines appeared to be characterized by a lower TOP1 protein amount than the normal like MCF10A cell line." (PMID 31783818, 2019). "However, FISH analysis of cancer cells showed a much higher proportion of TOP1 amplification (> 30% of BC patients had gene copy numbers > 4)." (PMID 31783818, 2019). "Taken together, TOP1/2 poisons, through their various modes of actions during replication and other DNA transactions, have been successfully exploited for chemotherapy of common human cancers." (PMID 31067275, 2019). "Top1 is currently a hot topic in the research of cancer treatment." (PMID 31167344, 2019). "However, cancer cells can resist TOP1 targeting therapies by overexpression of PDB repair factors such as TDP1." (PMID 29898404, 2018).
cancer (continued). "Furthermore, the widely-used anti-cancer drugs, camptothecin (CPT) and etoposide (ETO), kill cancer cells by trapping Top1- and 2-ccs, respectively." (PMID 30170832, 2018). "We have recently introduced another approach for Top1 quantitation in cancer cells." (PMID 28077117, 2017). "Thus, this study adds to the growing knowledge about anti-cancer resistance mechanisms for camptothecins and the new class of indenoisoquinoline Top1-targeting drugs." (PMID 27029323, 2016). "In addition, TOP1 poisons were found to sensitize cells to radiation therapy, increasing their potential usefulness in cancer therapies." (PMID 27181710, 2016). "The positive association between TOP1 amplification and expression of Top1 mRNA and protein was confirmed by another study, and Top1 mRNA and protein expression have been shown to correlate well in the NCI-60 cancer cell line panel." (PMID 27029323, 2016). "The resistant cell lines were analyzed for cross-resistance to other anti-cancer drugs, global gene expression, growth rates, TOP1 and TOP2A gene copy numbers and protein expression, and inhibition of the breast cancer resistance protein (ABCG2/BCRP) drug efflux pump." (PMID 26801902, 2016). "The results suggest that, irrespective of cancer types, toptecan sensitivity is generally associated with Top1 (p-value = 7.7e-03) and WRN (p-value = 2.27e-06) mRNA expression." (PMID 26959889, 2016). "The role of miR-149 playing in cancer prognosis may function through DNA topoisomerases 1 (TOP1) pathway, according to the results from luciferase reporter assays." (PMID 27825117, 2016). "The correlations among TOP1 levels, cancer staging, and overall survival (OS) were analyzed." (PMID 26207989, 2015). "However, increased DNA repair activities in cancer cells can make TOP1 inhibitors less effective, so silencing of repair pathways in conjunction with the use of TOP1 inhibitors offers an attractive new means for cancer control." (PMID 26287259, 2015). "The DNA topoisomerase I inhibitor β-lapachone is one of the phytometabolites that induces a cell-cycle delay at G1/S phase before inducing either apoptotic or necrotic cell death in a variety of human carcinoma cancers." (PMID 26309132, 2015). "The ends of TOP1 nicks created by the TOP1 inhibitors have a 5′-hydroxyl and 3′-phosphate-protein intermediate, which is a property that may be exploited for cancer therapy." (PMID 24573252, 2014). "As cleavage of PARP eventually results in cancer cell death, this compensatory action of TOP1 reduction in etoposide-treated cancer cell may therefore increase the chemotherapeutic sensitivity." (PMID 24103454, 2013). "It is probable that the compensatory activation of PARP cleavage may be initiated when TOP1 activity has also been suppressed in etoposide-treated cancer cells since previous study has found PARP cleavage in cells with TOP1 being inhibited." (PMID 24103454, 2013). "After that, a number of other studies also demonstrated shikonin’s potential anticancer activities in several human tumors through inhibiting cancer cell growth, inducing apoptosis, inhibiting DNA topoisomerase I/II activity, anti-telomerase activity and antiangiogenesis." (PMID 24260077, 2013). "Elevated levels of Top1 have also been reported in various other cancers." (PMID 24400218, 2013). "However, as it was found that TOP1/TOP2A expression in cancer cells are important in determining the cellular response to chemotherapeutics." (PMID 24103454, 2013). "In addition, LP was shown to inhibit DNA synthesis and to target DNA topoisomerase I triggering apoptosis in cancer cells." (PMID 22973400, 2012). "Drugs targeting topoisomerase I (Top1) are used in a number of cancer chemotherapy regimens." (PMID 23284638, 2012). "Topoisomerase I (Top1) is a proven target for cancer therapeutics." (PMID 23284638, 2012). "Furthermore, WRN expression is thought to affect sensitivity to DNA topoisomerase I inhibitors in cancer therapy." (PMID 22797812, 2012).
cancer (continued). "A reduction in the levels of DNA topoisomerase I in human fibroblasts after camptothecin treatment could be mediated by proteasome-dependent degradation as previously reported for some cancer cell lines." (PMID 19445707, 2009). "Therefore, during drug therapy, blocking the Top1 may be crucial for inhibiting the proliferation of cancer cells." (PMID 39264927, 2024). "Finally, hyper cleavage Top1 alleles that are expressed in human cancers have not yet been described." (PMID 39408578, 2024). "Consequently, cancer cells are highly sensitive to TOP1 inhibitors." (PMID 38783957, 2024). "Therefore, the combination of TDP1 inhibitors and TOP1 poisons could synergistically be more effective for the treatment of cancer." (PMID 39109293, 2024). "Importantly, TOP1 is the target of the camptothecin family of anticancer agents that binds to and reversibly stabilizes the covalent TOP1-DNA complex, resulting in double stranded DNA breaks and apoptosis, preferentially in cancer cells that often overexpress TOP1." (PMID 36651963, 2023). "The formation of TOP1cc can be facilitated by the interaction of TOP1 with oxidised bases such as 7,8-dihydro-8-oxoguanine (8-oxoG), suggesting that the accumulation of oxidative stress and reactive oxygen species (ROS) in ALT cancers might serve as a pathway to trap TOP1." (PMID 36940725, 2023). "TOP1 inhibitors could be used to kill cancer cells, and are most effective in HR-defective cells." (PMID 38012183, 2023). "Our data provide strong evidence that combining ATR and TOP1 inhibitors in cancer cells triggers robust immune response signaling and secretion of pro‐inflammatory factors, and thus might transform “cold” tumors into “hot” tumors, which are more likely to respond to systemic immunotherapy." (PMID 35957613, 2023). "Therefore, further identification of key genetic factors that participate in the cellular response to TOP1-induced damage and characterize the relationship among these repair factors should provide a rational and optimal application of TOP1 poisons in cancer therapy." (PMID 35869071, 2022). "However, the elicited mechanisms by which TOP1 poisons kill cancer cells are not fully understood." (PMID 35794238, 2022). "TDP1 inhibitors could potentiate the anticancer activity of TOP1 inhibitors and as such, they would represent a new therapeutic class that could potentially be used for the treatment of cancer in combination with current TOP1 inhibitors." (PMID 36051621, 2022). "Thus, overall the findings suggest that Top1 poisons, at low dosage, may have an immune-stimulatory effect contributing to its established antitumour activity in cancer patients." (PMID 36114513, 2022). "Previous reports suggested that anti-cancer drugs such as cisplatin and hydroxyurea induced mRNA expression of CXCL9/10/11 through cell cycle-specific DNA damage in human cancer cells, and the DNA topoisomerase I inhibitor, irinotecan, is also known to cause cell cycle-specific DNA damage." (PMID 34413454, 2021). "High affinity and strong specificity of the copper complex with Top1–DNA complex might play an important role in the inhibition of cancer cell activities such as replication, and alteration in transcription, redox mechanism and DNA repair mechanism with association to the cell death mechanism." (PMID 33019623, 2020). "This could rise questions to the rationale of using TOP1 as a target in cancer treatment." (PMID 31783818, 2019). "Alternatively, since TOP1 poisons are thought to target only those TOP1 molecules that are actively catalyzing the topoisomerase reaction on the DNA, increasing TOP1 activity in cancer cells may enhance their sensitivity to killing by TOP1 poisons." (PMID 27181710, 2016). "Therefore, developing effective TOP1 inhibitors not only provides powerful tools to study DNA replication and repair but also establishes a foundation to devise new synthetic lethal strategies for efficient cancer treatments." (PMID 26287259, 2015).
cancer (continued). "Hence, previous studies revealed that several acetogenins act as a DNA topoisomerase I poison, arrested cancer cells at the G1 phase and induced apoptotic cell death in a Bax-and caspase-3- related pathways, and inhibited NADH-ubiquinone oxidoreductase (complex I) in mitochondria." (PMID 25539720, 2014). "Additionally, an association between TOP1 copy numbers and irinotecan effect should subsequently be tested in the other cancer types not currently being treated with irinotecan." (PMID 24400218, 2013). "Additionally, TOP1 is targeted by topoisomerase inhibitors to treat a wide variety of cancers." (PMID 24068912, 2013). "Camptothecins are potent anti-cancer drugs that block cell division through several mechanisms including the introduction of DNA replication-dependant double-stranded breaks which trigger apoptosis, and down regulation of Top-1 by activation of proteasome pathways." (PMID 21909362, 2011). "We previously showed that topotecan, a chemotherapeutic drug and topoisomerase I (TOP1) inhibitor, binds to ribosomal protein RPL15 and induces the secretion of DAMPs from cancer cells, which activate cGAS-STING signaling in dendritic cells." (PMID 41276688, 2025). "In vitro assays across diverse cancer cell lines assessed cytotoxicity, DNA damage response (DDR) activation, and TOP1 degradation." (PMID 41077566, 2025). "Inhibitors of the DNA topoisomerase 1 (TOP1) and 2 (TOP2A and TOP2B) have shown considerable potential as therapeutic agents against cancers, including HNSCC." (PMID 38920662, 2024). "TOP1 and TOP2 have been widely studied and are considered to be highly relevant targets for the cancer therapy." (PMID 37088855, 2023). "Here, we investigate the intrinsic expression of STING in cancer cells and evaluate the value of the combination of ATR and TOP1 inhibitors in enhancing antitumor immunity." (PMID 35957613, 2023). "Given the widespread use of TOP1 and TOP2 inhibitors in cancer therapy, the data obtained in the present study raise the possibility that TDP2 is a critical etiological factor in the response of tumors to TOP1 and TOP2 inhibitors." (PMID 37392847, 2023). "Our study not only uncovers a replication-coupled ubiquitin-proteasome pathway for the repair of TOP1-DPCs but also provides molecular and translational rationale for combining TOP1 inhibitors and pevonedistat for CRC and other types of cancers." (PMID 37353483, 2023). "The possible use of the combination of TOP1 poison and the PARP inhibitor in cancer treatment is widely discussed." (PMID 36982223, 2023). "Changes under the treatment with TOP1 and TDP1 inhibitors separately were found in the signaling pathways for the development of cancer, DNA repair, cell cycle control and apoptosis, and the proteasome." (PMID 36982223, 2023). "Several authors discuss the rationale behind the use of the combination of TOP1 poison and TDP1 and PARP inhibitors in cancer treatment." (PMID 36982223, 2023). "We have previously shown that PPRHs are a valuable tool for gene silencing of relevant cancer targets such as dihydrofolate reductase, survivin, BCL2, TOP1, mTOR, MDM2, and MYC." (PMID 37108234, 2023). "TDP1 plays a crucial role in the repair of DNA lesions formed by antitumor drugs such as the TOP1 inhibitors camptothecin, topotecan (a TOP1 poison in clinical use), and irinotecan; therefore, TDP1 is a promising target for adjunctive cancer treatment." (PMID 36982848, 2023). "Gene expression activation is present only in cancer cell lines expressing STING (i.e., HeLa cells), while cells with a marked reduction of STING are resistant to Top1 poison induction of immune genes." (PMID 36114513, 2022). "Uncovering the mechanism and predictive markers for TOP1 inhibitor sensitivity will help improve the clinical use of TOP1 inhibitors and expand the scope of TOP1-targeted therapy in the treatment of TNBC and other cancers." (PMID 35844787, 2022).
cancer (continued). "Top1 is targeted by the widely used anti-cancer chemotherapeutic camptothecin (CPT) and its derivatives, which stabilize Top1 covalently attached on a DNA nick and prevent the re-ligation step." (PMID 35291312, 2022). "Survival analysis showed that the CNVs of TOP2B in 13 cancer types, TOP3B in 7 cancer types, TOP2A in 6 cancer types, TOP1MT in 6 cancer types, TOP3A in 5 cancer types and TOP1 in 5 cancer types significantly correlated with overall prognosis." (PMID 36288358, 2022). "FL118 inhibition of cancer cell growth occurs at high pM to low nM levels, whereas FL118 inhibition of Top1 activity occurs at μM levels." (PMID 35604033, 2022). "Topotecan (TPT) is a DNA topoisomerase I inhibitor that has shown anti-cancer effects on gastric cancer and the results from its testing suggest that ASCT2 is an anti-cancer target for this compound, as it presented the same effects as ASCT2 knockdown." (PMID 33429909, 2021). "An interesting target for cancer treatment is TDP1, which plays a key role in the removal of DNA damage produced by TOP1 inhibition by clinically important anticancer drugs (irinotecan, Tpc) as well as removal of DNA damage caused by other anticancer drugs." (PMID 34356597, 2021). "As the anti-cancer effect of CPT and its analogous are strictly dependent on the generation of TOP1cc, any drug preventing TOP1 from cleaving DNA will counteract its cytotoxic effect." (PMID 34300575, 2021). "Such interaction was demonstrated to modulate TOP1 activity and CPT sensitivity of a broad range of cancer cell lines." (PMID 32423158, 2020). "Taken together, these results suggest that FAM111A protects cells from several anti-cancer drugs, especially PARP and TOP1 inhibitors." (PMID 32165630, 2020). "The cytotoxicity of TOP1ccs is also exploited in cancer therapy by the widely used class of anti-cancer drugs, known as camptothecins (CPT), which stabilise TOP1ccs by binding the TOP1–DNA interface." (PMID 32152270, 2020). "It was previously demonstrated that the tumor suppressor p14ARF can interact with and regulate the activity of phosphorylated isoforms of TOP1 and thereby affect the CPT sensitivity in cancer cells." (PMID 32423158, 2020). "The results of the current study are the first to show that inhibition of cancer invasion by CKD-602, a TOP1 inhibitor." (PMID 31138113, 2019). "Top1 is the target of a widely used anti-cancer chemotherapeutic named campthothecin (CPT) and its derivatives, which bind to Top1-DNA covalent complex and inhibits the re-ligation step." (PMID 26527723, 2016). "Nonetheless, the protective effect of TOP1 K391 and K436 SUMOylations against TOP1-induced DNA damage during transcription also strongly points toward the possibility that a SUMOylation defect on these residues could lead to genome instability, mutagenesis, and cancer." (PMID 27181710, 2016). "TOP1, TOP2A and TOP2B levels in several human cancers were reported to be higher than those of normal or benign tissues, which was in accordance to the results from Oncomine." (PMID 27315793, 2016). "The TOP1 inhibitor camptothecin (CPT), first isolated from the Chinese tree Camptotheca acuminate, was clinically used for cancer treatment long before it was identified as a TOP1 inhibitor." (PMID 26287259, 2015). "For example, the RNA splicing and processing theme involves 2,009 pSNVs in 652 genes, including 38 known cancer genes such as BRCA1, RBM15, CDK12, CDC73 and TOP1 (FDR p = 1.3e − 06, Fisher's exact test), as well as candidate cancer genes." (PMID 24089029, 2013). "As the content of TOP1 could predominantly regulate sensitivity of cancer cells in response to TOP1 poisons, suppression of TOP1 expression by miR-23a is therefore capable to reduce the content of TOP1-DNA covalent complex through removing available TOP1 from the system." (PMID 24103454, 2013).